MYC (MYC proto-oncogene, bHLH transcription factor)
Diseases named in the same sentence as MYC in open-access papers (continued):
Sharing a sentence is not in itself a finding about the gene and the disease.
medulloblastoma (continued). "Group 3 (G3) is one of the most common and aggressive subtypes of the paediatric cerebellar tumour Medulloblastoma (MB), primarily driven by the MYC oncogene." (PMID 41198629, 2025). "The reprogramming of pyrimidine metabolism in MYC-driven medulloblastoma represents an unappreciated therapeutic strategy and a potential new class of treatments with stronger cancer selectivity and fewer neurotoxic sequelae." (PMID 41221269, 2025). "Particularly, MYC overexpression correlates with poor clinical outcomes and worse survival in a wide range of cancers including medulloblastoma." (PMID 39779613, 2025). "Another team has also combined JQ1 and milciclib and found that they synergistically reduced MYC-driven medulloblastoma cell survival and prolonged survival in allografted mice." (PMID 40862786, 2025). "MTOR signaling itself is another key regulator of protein synthesis which is frequently deregulated in various cancers, including MYC-addicted cancers and medulloblastoma." (PMID 39779613, 2025). "In medulloblastoma, for instance, LINC00888 encodes a microprotein that is significantly upregulated in MYC-driven medulloblastoma samples and facilitates the survival of MB cells." (PMID 39859408, 2025). "Recently, a combination of BET protein inhibitor JQ1 with a histone deacetylase inhibitor (panobinostat) synergistically induces anti-cancer effects in MYC-amplified medulloblastoma in vitro and in vivo." (PMID 39779613, 2025). "Direct evidence for such feedback has been demonstrated in MYC-driven medulloblastoma models, where increased glycolytic flux elevates intracellular acetyl-CoA levels, enhancing histone H3K27 acetylation and upregulating proliferation-associated genes." (PMID 40868156, 2025). "For example, medulloblastomas are frequently associated with mutations in CTNNB1, PTCH1, MYC, and MYCN, while the H3K27M mutation characterizes diffuse midline gliomas (DMGs)." (PMID 40647519, 2025). "In conclusion, combining BET and CDK2 inhibition offers a potential strategic therapy for targeting MYC-dependent medulloblastoma among pediatric patients." (PMID 38183103, 2024). "Ultimately, these findings demonstrate the efficacy of single-cell multiome analysis in elucidating resistance mechanisms and identifying novel target pathways for MYC-driven medulloblastoma." (PMID 39711559, 2024). "Research has shown that HDACis and PI3K antagonists can effectively inhibit the growth of MYC-driven medulloblastoma both in vitro and in vivo, and they suggest that inhibitors of class I HDACs are effective against this type of medulloblastoma." (PMID 38822399, 2024). "Preclinical studies of JQ1 in medulloblastoma have shown increased survival and anti-proliferative effects, particularly in MYC-expressing cells." (PMID 39766049, 2024). "MYC-driven medulloblastoma (MB) is a highly aggressive cancer type with poor prognosis and limited treatment options." (PMID 39574899, 2024). "The observed differences in the molecular weight of MYC between the medulloblastoma and SebCA lines is likely a consequence of post-translational modifications and cleavages." (PMID 39337668, 2024). "MYC amplification, which is a prevalent driver of group 3 medulloblastomas, and LOH deletion of a tumor suppressor, TSC1, was found in the PD2105 and PD2110 patients, respectively." (PMID 39322849, 2024).
medulloblastoma (continued). "Our SebCA01, 02, and 03 cells all showed MYC protein expression (after normalization to loading using actin) similar to the expression in D425 medulloblastoma, and approximately twice that in D283 cells." (PMID 39337668, 2024). "A subset of Group 3 medulloblastoma highly express MYC protein, and two medulloblastoma lines (D283 and D425), reported to show an elevated MYC expression, were used as positive controls." (PMID 39337668, 2024). "In conclusion, our data suggest that the CDK8 inhibitor RVU120 is a promising agent for MYC-driven medulloblastoma therapy and provides a mechanistic basis for future research." (PMID 39574899, 2024). "In aggressive group 3 medulloblastoma, a childhood brain tumour, DHODH activity is linked to the MYC gene, which drives tumour growth." (PMID 39766063, 2024). "MYC protein has been detected in each of our three cell lines by Western blot, at similar or greater levels as in two established Group 3 medulloblastoma cell lines that are known to be MYC-driven." (PMID 39337668, 2024). "For example, in MYC-driven models of medulloblastoma, BET inhibition, via JQ1, in combination with CDK inhibitor, milciclib, diminished proliferative markers and induced apoptosis." (PMID 38183103, 2024). "Minnelide, a prodrug of triptolide, targets MYC to attenuate the proliferation and leptomeningeal spread of group 3 medulloblastoma, supporting its translation for treatment of patients in this cohort." (PMID 38885332, 2024). "Patients with MYC-amplified Group 3 medulloblastoma (MB) (subtype II) show poor progression-free survival rates." (PMID 38184819, 2024). "PVT1–MYC and PVT1–NDRG1: resulting from chromothripsis events in medulloblastoma, PVT1–MYC fusion causes MYC overexpression, leading to continuous oncogenic activity." (PMID 38919532, 2024). "Medulloblastoma (MB) patients with MYC oncogene amplification or overexpression exhibit extremely poor prognoses and therapy resistance." (PMID 38200580, 2024). "Although this experience did not suggest a survival advantage with this approach, it allowed a better identification of high-risk patients such as patients with metastatic disease or subtype III or medulloblastoma with MYC amplification." (PMID 38132264, 2023). "Together, our studies demonstrate that CTDNEP1 is a tumor suppressor in highly aggressive MYC-driven medulloblastomas by controlling MYC activity and mitotic fidelity, pointing to a CTDNEP1-dependent targetable therapeutic vulnerability." (PMID 36765089, 2023). "Triggering the MYC can be crucial and defines the metabolism in medulloblastomas across their sub-groups, according to numerous lines of evidence." (PMID 37894287, 2023). "While overexpression of MYC has previously been shown to drive medulloblastoma formation in mice, the functional significance of SMARCA4 mutations and their suitability as a therapeutic target remain largely unclear." (PMID 37919824, 2023). "For the medulloblastoma data, scMSGL efficiently captured the significant roles that key oncology markers MYC and OTX2 play in the transcriptional regulation of metabolic genes." (PMID 37016281, 2023). "More effective radiation sparing strategies are needed for group 3 medulloblastoma to reduce disseminated failures in the MYC-amplified patients in particular." (PMID 37022464, 2023). "The efficacy of EPZ015666 was determined on the three MYC-amplified medulloblastoma cell lines (HD-MB03, D-283, and D-341)." (PMID 38136401, 2023). "One example of this is in medulloblastoma, where MYC was shown to increase its own expression by binding PVT1 in a positive feedback loop." (PMID 37958407, 2023). "Based on these observations, the authors tried to reveal the detailed mechanism of CTDNEP1 as a tumor suppressor in aggressive MYC-driven medulloblastomas." (PMID 37374122, 2023).
medulloblastoma (continued). "Intriguingly, high MYC expression in group 3 medulloblastoma has been shown to inversely correlate with the NOTCH signaling signature and reflects early fetal cerebellar development." (PMID 37175848, 2023). "OTX2 can directly activate c-MYC expression in medulloblastoma via cis-regulatory elements in MYC promoter." (PMID 37181651, 2023). "Treatment with the orally bioavailable BRD4 inhibitor MK-8628 suppresses medulloblastoma cell proliferation and induces apoptosis by reducing MYC expression, and MK-8628 suppresses medulloblastoma tumor progression in preclinical models." (PMID 38135679, 2023). "Treatment with PRMT5 inhibitor EPZ015666 resulted in decreased MYC protein levels and medulloblastoma cell growth, indicating that PRMT5 inhibitors are potential treatments for MYCN-driven cancer." (PMID 36770809, 2023). "We found that high levels of PRMT5 not only mirror MYC expression but also correlate with poor outcomes in Group 3 medulloblastoma patients." (PMID 38136401, 2023). "This overrepresentation of MYC-amplified group 3 medulloblastomas in the literature is, in fact, a reflection of the overabundance of cell lines that mimic this specific molecular profile." (PMID 37568705, 2023). "PRMT5 also represents a requisite driver of tumor progression in SHH-medulloblastoma and MYC-amplified medulloblastoma." (PMID 38136401, 2023). "We recently reported that PRTM5 is a critical regulator MYC oncoprotein in an MYC-amplified (Group 3) medulloblastoma." (PMID 38136401, 2023). "This confirms that OTX2 is functionally cooperating with MYC to regulate gene expression in medulloblastoma." (PMID 37016281, 2023). "PRMT5 plays a key role in cell functions and processes in MYC-driven medulloblastoma by stabilizing the MYC protein." (PMID 38136401, 2023). "Studies in medulloblastoma have indicated that MYCN binds MIZ-1 with a lower affinity compared with MYC, with consequences for MIZ-dependent repression in different subtypes of medulloblastoma." (PMID 37175848, 2023). "Another miRNA that comprises a potential target is the pro-tumorigenic and pro-metastatic miR-183~96~182 complex, which was found to be upregulated in MYC-amplified medulloblastomas and to be an upstream inducer of PI3k/mTOR signaling." (PMID 37568705, 2023). "In fact, local enhancer hijacking of GFI1 and distal enhancer hijacking of GFI1B drive medulloblastoma growth, either by cooperating with MYC to drive group 3 tumors or with other drivers to promote group 4 medulloblastoma development." (PMID 37568705, 2023). "A similar PLK1/Fbxw7/Myc axis was also identified in c-MYC-driven medulloblastoma, with PLK1 antagonizing Fbxw7-mediated c-Myc degradation." (PMID 36902175, 2023). "Co-treatment with MK-8628 and the PLK1 inhibitor Volasertib, which targets MYC protein for degradation, shows synergistic anti-medulloblastoma effects in vitro and in preclinical models." (PMID 38135679, 2023). "RMT5 inhibitors can potentially disrupt MYC’s function, impeding tumor progression and offering a target therapeutic approach to treat MYC-amplified medulloblastoma." (PMID 38136401, 2023). "The treatment increases cell death in synergy with cisplatin and demonstrates potential for targeting MYC-driven medulloblastoma." (PMID 36869047, 2023). "Here, we identify PLK1 as a potential co-target for a combination therapy with the class I HDACi entinostat in MYC-amplified medulloblastoma and investigate synergistic interactions in vitro and in vivo." (PMID 37183219, 2023). "The colocalization of PRMT5 and MYC suggests that PRMT5 forms a complex with MYC and supports its stabilization in MYC-amplified medulloblastoma cells." (PMID 38136401, 2023).
medulloblastoma (continued). "Here, we generate an immunocompetent transgenic mouse model with regulatable MYC that develop clonal tumors that molecularly resemble photoreceptor-positive Group 3 medulloblastoma." (PMID 36869047, 2023). "EPZ015666 significantly downregulates the higher expression of PRMT5 and MYC in medulloblastoma cells, suggesting it has therapeutic potential for MYC-driven medulloblastoma." (PMID 38136401, 2023). "Our lab recently analyzed the localization of the PRMT5 in tumor tissues of medulloblastoma patients as well as in MYC-amplified cell lines." (PMID 38136401, 2023). "Specifically, the BRD4 inhibitor, JQ1, was shown to reduce the proliferation of group 3 medulloblastoma cells with MYC amplification and to prolong the survival of mouse models with tumors having these characteristics." (PMID 37568705, 2023). "MYC-driven medulloblastomas are highly aggressive childhood brain tumors, however, the molecular and genetic events triggering MYC amplification and malignant transformation remain elusive." (PMID 36765089, 2023). "In this way, we identified the MYC oncoprotein to be significantly inactivated, both in D283 cells following YB-1 knockdown (Z score = −2.1) and in medulloblastoma patients with low YB-1 gene expression." (PMID 36831428, 2023). "In a parallel fashion, a large genomic analysis of MYC-driven group 3 medulloblastoma revealed an elevated expression of the inhibitory GABA-A receptor subunit alpha 5 (α5-GABAA)." (PMID 37568705, 2023). "The interplay of chromatin remodeling, MYC overexpression, and histone deacetylase (HDAC) inhibitors have suggested therapeutic strategies for MYC-driven medulloblastoma." (PMID 37627881, 2023). "Group 3 medulloblastomas often exhibit MYC overexpression and have the most dismal clinical diagnosis of the four medulloblastoma subgroups, with a survival rate of less than 60%." (PMID 38136401, 2023). "MYC-driven medulloblastoma has extreme metastatic potential and is often resistant to multipronged treatment." (PMID 38136401, 2023). "The expression of miR-193a inhibited growth, oncogenicity, and radiation sensitivity of medulloblastoma cells with increased expression of MYC." (PMID 37443682, 2023). "In a similar fashion, a novel in silico drug screening method, named DiSCoVER, predicted a potential role for CDK inhibitors in MYC-activated group 3 medulloblastomas." (PMID 37568705, 2023). "Compared to MYCN-expressing brain tumors driven from the same promoter, pronounced ARF silencing is present in our MYC-expressing model and in human medulloblastoma." (PMID 36869047, 2023). "MYC-driven medulloblastomas have extreme metastatic potential and are often resistant to multipronged treatment." (PMID 38136401, 2023). "Lately, a synthetic mRNA-driven strategy was used to develop the MYC-driven medulloblastoma model mimicking the Group 3 subtype." (PMID 36831595, 2023). "HDAC inhibitors are another potential therapeutic option for medulloblastomas and are particularly effective against established MYC-driven medulloblastoma cell lines and patient-derived xenografts." (PMID 37568705, 2023). "One challenge will be to determine if this effect is recapitulated in other cancers with recurrent MYCN amplification such as medulloblastoma and neuroendocrine prostate cancer or in the numerous cancers in which MYC is altered." (PMID 37958555, 2023). "While glucose metabolism in group 3 medulloblastomas and MycN-driven medulloblastomas in mice have yet to be investigated, it is likely that MYC reconfigures the metabolism to favor glycolysis in these tumors, as it does in other malignancies." (PMID 37894287, 2023). "This physical interaction of PRMT5 and MYC implies a potential role of PRMT5 in medulloblastoma tumorigenesis." (PMID 38136401, 2023).
medulloblastoma (continued). "This study was subsequently reported by Asuthkar's team, which further found that the overexpression of miR-29 in MYC+ medulloblastoma cells mediated the downregulation of B7-H3 and inhibited angiogenesis in medulloblastoma." (PMID 35909469, 2022). "The prominence of arginine biosynthesis in the pathway impact analysis highlights the upregulation of the citrulline–arginine cycle, in both MYC-driven medulloblastoma orthotopic xenograft models compared to normal brain." (PMID 35267619, 2022). "Compared to normal brain, MYC-amplified medulloblastoma orthotopic xenograft tumors showed upregulation of the TCA cycle as well as the synthesis of nucleotides, hexosamines, amino acids and glutathione." (PMID 35267619, 2022). "In the brain and orthotopic MYC-driven medulloblastoma tumor in addition to m + 1, we also detected at a much lower level in the orthotopic tumor, m + 2, m + 3 and m + 5 glutamate." (PMID 35267619, 2022). "Our data suggest there is very little glutamine carbon that contributes to the TCA cycle in MYC-amplified medulloblastoma in vivo." (PMID 35267619, 2022). "These HE stained sections demonstrate that the orthotopic xenograft tumors used in our study grew in the native microenvironment, with histology similar to that of human primary MYC-amplified medulloblastoma." (PMID 35267619, 2022). "No activity was observed for gemcitabine monotherapy in the group 3/MYC‐amplified medulloblastoma model (RA‐021)." (PMID 34927798, 2022). "Principal component analysis showed that the metabolic profiles of brain and flank high-MYC medulloblastoma tumors clustered closely together and separated away from normal brain and in vitro MYC-amplified cells." (PMID 35267619, 2022). "Medulloblastoma (MB) patients with MYC oncogene amplification or overexpression exhibit extremely poor clinical outcomes and respond poorly to current therapies." (PMID 36357906, 2022). "We performed comprehensive metabolic studies of human MYC-amplified medulloblastoma by comparing the metabolic profiles of tumor cells in three different conditions—in vitro, in flank xenografts and in orthotopic xenografts in the cerebellum." (PMID 35267619, 2022). "We performed comprehensive metabolic profiling of MYC-amplified medulloblastoma and found increased reliance on potentially targetable pathways." (PMID 35267619, 2022). "MYC-amplified medulloblastoma has a poor prognosis, and the metabolism of MYC-amplified medulloblastoma is poorly understood." (PMID 35267619, 2022). "This work also confirmed and extended our prior finding that glutathione was upregulated in MYC-amplified medulloblastoma compared to normal brain." (PMID 35267619, 2022). "The work presented here also identifies some key metabolic differences between normal cerebellum and cortex and MYC-amplified medulloblastoma tumors." (PMID 35267619, 2022). "The poor prognosis for “Group 3”, MYC-amplified medulloblastoma patients and the severe complications faced by survivors due to the intensity of the therapy they receive indicate an urgent need for more effective and less toxic therapies." (PMID 35267619, 2022). "Principal component analysis of metabolomes found distinct metabolic profiles in normal brain (cortex and normal contralateral cerebellum) compared to MYC-amplified medulloblastoma D425MED and MED211 orthotopic tumors." (PMID 35267619, 2022). "Based on the abundance of m + 1 glutamate and the absence of m + 6 glutamate in orthotopic tumors, we conclude that the glutaminase II pathway is the main pathway utilizing glutamine in MYC-amplified medulloblastoma." (PMID 35267619, 2022). "Rather than being reliant on glutamine from the microenvironment, we found that MYC-amplified medulloblastoma tumor cells synthesized glutamine." (PMID 35267619, 2022). "MYC amplification is an independent prognostic factor for the most aggressive subgroup (Group 3) of pediatric medulloblastoma (G3 MB)." (PMID 36473869, 2022).